MMP23A (matrix metallopeptidase 23A (pseudogene))
Synonyms: MIFR; formerly MMP21
Gene: Transcribed unprocessed pseudogene on chromosome 1 (1,699,942 to 1,701,782, forward strand). Ensembl gene ENSG00000215914.
Diseases named in the same sentence as MMP23A in open-access papers:
MMP23A is named in the same sentence as 3 diseases in open-access papers, as found by Europe PMC text mining. Sharing a sentence is not in itself a finding about the gene and the disease. The quoted sentences say what the papers report.
tumor (4 papers, 2015 to 2021). "We found that MMP1, MMP3, MMP7, MMP9-MMP12, and MMP14 were significantly upregulated in tumor tissue, while MMP15–MMP17, MMP19–MMP21, MMP23A, MMP23B, and MMP25–MMP28 were significantly downregulated in tumor tissue." (PMID 34804973, 2021). "MMP23 is a member of matrix metalloproteinase family (MMP23A, MMP21, MMP23B, MMP22) that participates in many aspects of tumour growth and metastasis." (PMID 26482227, 2015).
cancer (1 paper, 2019). A tumor composed of atypical neoplastic, often pleomorphic cells that invade other tissues. "Some MMPs had very high numbers of transcripts present (gene cluster A), while six MMPs in gene cluster C (MMP27, MMP21, MMP20, MMP26, MMP23A, and MMP8) featured scant numbers of transcript copies across any cancer tissue." (PMID 31200666, 2019).
MMP23A also shares sentences with these, for which no sentence is quoted: thyroid carcinoma (1 paper).